CD4 (CD4 molecule)
Diseases named in the same sentence as CD4 in open-access papers (continued):
Sharing a sentence is not in itself a finding about the gene and the disease.
Granuloma (continued). "The responsiveness of CD4+ T cells to TLR9 ligands in the microenvironment of granuloma may play a significant role in the inflammatory response." (PMID 37406035, 2022). "In up to 75% of patients, biopsy would reveal primary collagen necrosis leading to characteristic pathognomonic necrotising or palisading granulomas and micro‐abscesses with mixed cellular infiltrates including mainly CD4+ T‐cells and macrophages as well as neutrophils, plasma cells and histiocytes." (PMID 36125112, 2022). "Some huDRAG-A2 granulomas appeared more classically organized, characterized by focal central necrosis, multinucleated giant cells, and foamy macrophages surrounded by a halo of CD4+ T cells." (PMID 36146734, 2022). "We first determined the numbers of CD4+ T cells in the regions of granulomas lung tissue." (PMID 36189368, 2022). "The granulomatous reaction to Beryllium is caused by the activation of CD4+ lymphocytes that recognize Beryllium and produce IL-2 and IFN gamma, activating the multinucleated phagocytes and starting the formation of granulomas in the interstitium and in the pulmonary lymph nodes." (PMID 35011621, 2021). "Some evidence also suggests that CD4+ Th1-like cells may contribute to the formation of granulomas, and anti-CTLA-4 therapy has been shown to increase the amounts of peripheral Th17 CD4+ cells that produce the proinflammatory cytokine IL-1720." (PMID 34413300, 2021). "However, SIV-induced reactivation was associated with more dissemination of lung granulomas that were permissive to Mtb growth resulting in greater bacterial burden within granulomas compared to CD4 depleted reactivators." (PMID 32730321, 2020). "Higher RNA SIV:CD4 RNA ratios were associated with granulomas from reactivated animals compared to non-reactivators and in granulomas with Mtb burden." (PMID 32730321, 2020). "Even more granular features of CD4+ T cell responses may account for the heterogeneity across individual granulomas within a host." (PMID 32793199, 2020). "Indeed, in the present study, global IL-4Rα−/− mice had impaired hepatic granuloma development alongside elevated serum IL-10 levels compared with wild-type control mice and CD4+ T cell specific IL-4Rα−/− mice." (PMID 31475014, 2019). "Microscopic observation of the immunofluorescent staining indicate that the in vitro granulomas constitute cell types such as: macrophages, monocytes, dendritic cells CD4 and CD8 T cells all of which contribute to the innate and adaptive immune responses against M. tb infection." (PMID 30258443, 2018). "Granuloma formation in S. mansoni infection is a CD4+ T lymphocyte-dependent process." (PMID 30057918, 2018). "However, potential other sources of CD154 exist, as various cells, including CD4+ T cells and fibroblasts, that are important cell components and functional players in granuloma progression." (PMID 28785137, 2017). "However, Kv induced granulomas have histologically been detected at 6–24 hrs and resulted in a CD4+ and CD14+ monocyte assembly at 48 hrs after intradermal inoculation." (PMID 28114394, 2017). "As peripheral CD4+ T cell counts decreased, M. tuberculosis presence within granulomas increased." (PMID 27462092, 2016). "The ability of ART to restore the CD4+ T-cell count and reduce IL-10 production within granulomas of coinfected persons may indirectly lead to reduced M. tuberculosis growth." (PMID 27462092, 2016). "We hypothesize that HIV directly kills CD4+ T cells within granulomas and that this worsens as HIV disease progresses." (PMID 27462092, 2016). "Furthermore, IL13 knock-out mice infected with S. japonicum showed less eosinophil and smaller CD4+ T-driven granulomas and were protected from the development of liver fibrosis." (PMID 26258681, 2015). "Thus, even in the absence of high bacterial burden, MAP infection prompted transferred CD4+ T cells particularly to inflammation and the formation of granulomas in liver tissue." (PMID 24728142, 2014).
Granuloma (continued). "CD8+ T cells, in addition to CD4+ T cells, have also been found in granulomas." (PMID 24885153, 2014). "CD4-expressing cells with lymphocyte morphology could be observed both within the granulomas and evenly spread out in the connective tissue." (PMID 25350593, 2014). "FoxP3+ CD4+ T cells are present in increased numbers in and around granulomas." (PMID 24882950, 2014). "CD4+ T lymphocytes play an important role in the development of granulomas." (PMID 24177566, 2013). "CD4+ cells predominated over CD8+ T cells in or around granulomas." (PMID 23464965, 2013). "Very high proportion of CD4+ T cells was noticed inside the granuloma of the control group." (PMID 22844392, 2012). "In addition, IL-17 is reported to play an essential role in the formation of granulomas in mice infected with BCG and reduced Th17 CD4 T cell numbers are associated with PPD-induced impaired cytokine response in patients with HIV." (PMID 22359547, 2012). "However, because the micro-environment of the intestines is favourable towards the expansion of CD4+FoxP3+Tregs, it is possible that CD4+FoxP3+Treg-mediated suppression of enteric granulomas is more apparent compared with their hepatic counterparts." (PMID 21858239, 2011). "Furthermore, relative increases of CD4+FoxP3+ cells within colonic granulomas are apparent during chronic disease." (PMID 21858239, 2011). "Finally, transfer of schistosome infection-expanded CD4+CD25+Tregs down-modulated the development of colonic granulomas, including collagen deposition." (PMID 21858239, 2011). "Therefore, CD4+CD25+FoxP3+Tregs appear to control Th2 colonic granulomas during chronic infection, and are likely to play a role in containing pathology during intestinal schistosomiasis." (PMID 21858239, 2011). "Granulomas are formed as a result of exaggerated cellular immune response to one or more external or self-antigens and a subsequent accumulation of activated macrophages and CD4(+ T cells at an inflammatory site." (PMID 21143835, 2010). "The immunopathology has been best studied in bronchoalveolar lavage fluid and lung disease in which early lesions consist of an alveolitis with a high proportion of activated CD4+ Th1 cells, which may precede granuloma formation." (PMID 18811966, 2008). "In diffuse infiltrates the CD8/CD4 T lymphocyte ratio was higher than in granulomas." (PMID 17989779, 2007). "Furthermore, the positive correlation between CD4+ T cell count in granulomas and the integrity of tuberculous granulomas explained, to some extent, the possible mechanisms behind the variation in clinical characteristics of HIV patients with different immune statuses when co-infected with TB." (PMID 39205309, 2024). "However, here, in single-cell transcriptomic analysis, the finding that macrophages of those with progressive disease have a higher expression of certain MHC II allele points more to their specific role, possibly in persistent activation of CD4 T-cells and maintenance of granuloma." (PMID 36543347, 2022). "However, the assessment of the quality of the CD4+ T cell response within the context of the lung and/or granuloma in animal models could serve as an adjunct in the development of a pre-clinical portfolio for promising vaccine candidates." (PMID 35493495, 2022). "The outcome of Mtb infection also relies on CD4+ Tregs that help maintain the delicate balance between pro- and anti-inflammatory CD4+ T-cell responses, which has been convincingly demonstrated by the induction of IL-10 and IL-17 in sterile granulomas in macaques." (PMID 32862519, 2020). "Finally, interleukin (IL)-2 and interferon gamma (IFN-γ) production by CD4 T cells was higher in patients with hepatomegaly, and chemokine receptor CCR5 known to be expressed on Th1 cells was shown to be higher on CD4 T cells in patients with granulomas, implying Th1 bias in these patients." (PMID 31803177, 2019).
Granuloma (continued). "Interestingly, both Mtb-specific CD4 T cells and CD4 T cells of irrelevant specificities were found in granulomas of Mtb-infected monkeys which could be explained by the DD recruitment model extended in this work." (PMID 31616407, 2019). "To determine whether the decrease in neutrophils, IL-17 and activated CD4+ T cells in the lungs of TLR2/9-/- mice resulted in reduced development of granulomas, we examined H&E stained lung sections from WT and mutant mice that had been exposed to SR for 3 weeks." (PMID 24023674, 2013). "Previous experiments have demonstrated that Mtb-infected dendritic cells produce CXCL10, which acts as a chemotactic factor for NK cells and T lymphocytes (both CD4+ and CD8+), that contribute to the formation of TB granulomas at the infection site." (PMID 40668059, 2025). "CD4 lymphocytes predominantly accumulated in the granulomas, whereas CD8 lymphocytes were found sporadically only at the periphery of the granulomas." (PMID 40226537, 2025). "In contrast, the LTBI group exhibited elevated levels of CD4 + and CD8 + T cells, suggesting a more effective immune containment mechanism that potentially restricts Mtb within granulomas and prevents systemic dissemination." (PMID 40524207, 2025). "Immunohistochemistry analysis of CD4, and CD8 in lung sections revealed significant differences in the distribution of these immune cells within the granulomas among different infected groups and sexes." (PMID 38999932, 2024). "There is also immunohistochemical evidence of IL-17 and IL-23R expression in granulomas and higher levels of ESAT-6–stimulated IL-17–producing CD4+ T cells in BAL." (PMID 38165044, 2024). "The analysis also concluded that CD3+, CD4+, or CD8+ T cells along with the macrophage counts within granulomas were highly variable." (PMID 39066368, 2024). "Accordingly, CD4 cells, CD8 cells, B cells, and other host cells were targeted within granulomas in which the RS ratio ISH was quantified." (PMID 39253081, 2024). "The granulomas were composed of abundant CD3+, CD4+ and CD8+ T cells but less CD20+ B cells and showed a focal pSTAT1 expression in the nuclei of multinucleated giant cells and CD4+ and CD8+ T cells." (PMID 38310187, 2024). "Secondly, in LTBI animal models, Simian Immunodeficiency Virus (SIV) infection usually leads to ATB, where SIV infection first depletes MTB-specific CD4+ T lymphocytes in granuloma tissues, and MTB-specific CD4+ T cells move less within granulomas." (PMID 39205309, 2024). "IL-17A is instrumental in granuloma formation and stability and recall of IFN-γ–producing CD4+ T cells to the lungs." (PMID 38165044, 2024). "TGF-β seems to contribute to poor IFN-γ secretion by CD4+ T cells, as blockade of TGF-β signaling in T cells resulted in improved IFN-γ production within granulomas, and lower bacterial burdens." (PMID 38165044, 2024). "Together, these data demonstrate that CD4+ and CD8+ T cells in granulomas from SIV-infected, ART-treated macaques are quite similar to those from macaques infected with Mtb alone." (PMID 37039653, 2023). "Sarcoidosis granulomas contain multinucleated giant cells, foamy macrophages, epithelioid macrophages, a rim of CD4 T cells, and sometimes CD8 T cells and B cells surrounding the granuloma rim." (PMID 37367586, 2023). "Disseminated patient skin biopsies also contained CD4 T cells in the middle and CD8 T cells in the mantle of granulomas." (PMID 37367586, 2023). "However, we did not observe a loss of CCR5+ CD4+ T cells in granulomas." (PMID 37039653, 2023). "Patient samples have revealed that CD4 T cells, CD20 B cells, and IFN-γ are present in the mantle regions of necrotizing Coccidioides granulomas." (PMID 37367586, 2023). "The number of CD4+ T cells was lower in VPM1002-, PDX- and NUOG-induced granulomas compared to BCG-induced granulomas, with significant (p ≤ 0.05) differences between BCG and NUOG." (PMID 36232295, 2022).
Granuloma (continued). "The frequency of CD4+ and CD8+ T cells that were producing the cytokines TNF-α- and IFNγ from lung granulomas, thoracic LNs, and lung tissue homogenates were measured as part of our previous study for the SIV+ group as a whole." (PMID 35467372, 2022). "While CD4+ T cells were evenly distributed throughout the inflammatory infiltrate in PDX- and NUOG-induced granulomas, there was a gradient in BCG- and VPM1002-induced granulomas, with lower numbers of CD4+ T cells towards the central necrosis." (PMID 36232295, 2022). "There was also no impact of 5-OP-RU administration on the magnitude of Mtb-specific CD4 and CD8 T cells in the blood, spleen, LNs, granulomas or instillation site lesions at necropsy." (PMID 34158594, 2021). "CD3+CD4+CD8+ T cells have distinct cytokine and cytolytic responses within PBMC, BAL, and lung granulomas compared to traditional CD4 and CD8 single positive T cells within M. tuberculosis infected cynomolgus macaques." (PMID 32730321, 2020). "During the acute phase, the SEA-specifically activated CD4+ Th cells release the Th1-type cytokines, IL-2 and IFN-γ, which mediate the establishment of early granulomas." (PMID 32132991, 2020). "Taken together, CD4 and CD8 T cells from Mtb/SIV granulomas have a more immune activated (more cytokines and granzyme B production) profile than Mtb/αCD4 and LTBI control groups and this was associated with the loss of control of latent infection." (PMID 32730321, 2020). "Mtb-specific CD4 T cell production of the Th1 cytokines IFN-γ and TNF-α is important for activating macrophages and promoting formation of granulomas in the lung for containment of Mtb." (PMID 31497018, 2019). "This immunity has been extensively studied and has become the “central dogma” of protective immunity mediated by macrophages, granulomas and production of IFN gamma by CD4+ T cells." (PMID 30283448, 2018). "On the other hand, smoking cessation was found to help restore type-1 immunity by rapidly improving lung APC functionality, enhancing the recruitment of CD4+ IFN-γ+ T cells into the lung, and promoting the granuloma formation." (PMID 29441064, 2018). "An intense staining for CD4, CD8, and CD86 molecules was observed in NAC-treated granulomas suggesting that reduction in the extent of necrosis and ROI production will maintain the viability of myeloid and lymphoid cells in the granulomas (2L, N, P, R, T)." (PMID 30258443, 2018). "The cell types that constituted in vitro granulomas from T2DM group were macrophages, monocytes, dendritic cells CD4 and CD8 T cells." (PMID 30258443, 2018). "Increase IFNγ & TNF-α levels and PMN cells & functions.Increase T helper CD4 T cells & CD8 T cells activity.Improve Ag- specific antibody response.Restored DTH response and Granuloma formation.Reduced IL-6 cytokine and bacterial load." (PMID 30534129, 2018). "Conclusively, an imbalance in T-cells within TB-induced granulomas mainly being composed of CD8+ cytotoxic T-cells, and few CD4+ T-helper cells down-regulates cell-mediated and humoral immunity to Mtb locally." (PMID 28713389, 2017). "CD4+ and CD8+ T lymphocytes were present throughout the sample from the dermal-epidermal junction and in granulomas." (PMID 28115669, 2017). "To determine the effect of coinfection on the cellular response within granulomas, we next investigated the numbers of CD3+, CD4+, and CD8+ T cells, monocytes (CD68 coverage), and neutrophils (CD15 coverage)." (PMID 27462092, 2016). "We hypothesize that this influx of neutrophils (a proinflammatory response) in LNs of patients with <50 peripheral CD4+ T cells/μL of blood ultimately led to the increased production of IL-10 (an antiinflammatory response), since their presence was positively correlated within caseous granulomas." (PMID 27462092, 2016). "Apart from CD4+T cells, CD8+T cells play a critical role in the control of L. donovani infection by contributing to the formation of granulomas in the liver of L. donovani infected mice." (PMID 27580076, 2016).
Granuloma (continued). "The majority with HIV were also receiving ART [15 of 28 (53%)]; the median CD4 count for those with HIV and granulomas was 135 cells/mm3 (IQR: 69, 226)." (PMID 25668620, 2015). "An elevated level of IL-17 has been found in granulomas in the lung, BAF, as well as circulating CD4+ T cells in patients with pulmonary sarcoidosis." (PMID 24885153, 2014). "Continuous cigarette smoke exposure locally, by not systemically, impairs APC accumulation and their production of TNF, IL-12, and RANTES, blunts the recruitment of CD4+IFN-γ+ T cells to the lung, and weakens the formation of granuloma." (PMID 23527127, 2013). "Granuloma-derived transforming growth factor-β (TGF-β) also inhibited IFN-γ production by CD4+ T cells during EVL, providing further evidence that regulatory mechanisms are operating with Leishmania-induced granulomas." (PMID 23423646, 2013). "On the other hand, smoking cessation was found to help restore type 1 immunity by rapidly improving the functionality of lung APCs, enhancing the recruitment of CD4+IFN-γ+ T cells to the lung, and promoting the formation of granuloma." (PMID 23527127, 2013). "The results of this study indicate that in vivo, post-septic CD4+ T cells mediate increased TH2 and decreased TH1 granuloma formation, which correlates with previously published studies." (PMID 21655295, 2011). "The results of this study indicate that post-septic CD4+ T cells exhibit a general propensity for mediating TH2 inflammatory processes, as evidenced by decreased TH1 and increased TH2 granuloma size." (PMID 21655295, 2011). "The proportion of CD4+CD25+FoxP3+Tregs: CD4+ cells in the mLN increased during chronic disease, while within colonic granulomas there was an approximate 4-fold increase." (PMID 21858239, 2011). "First, CD4+ and CD8+ Tregs were increased at the site of infection, both in mycobacterium induced granulomas and at sites of extrapulmonary TB compared to the circulation." (PMID 20195504, 2010). "CD4+ and CD8+ T-lymphocytes, as well as a few B-lymphocytes, form a characteristic ring at granuloma periphery." (PMID 18811966, 2008). "The marrow granuloma in our case was positive for T cells (CD45, CD3, CD4, and CD8), histiocytes (CD68) and few plasma cells (CD138)." (PMID 17594503, 2007). "The number of cells in granulomas did not change following CD4 or CD8β depletion but significantly increased following depletion of all CD8α+ lymphocytes." (PMID 39912921, 2025). "Granuloma is non-necrotizing with a tightly packed central region comprising multinucleated giant cells, epithelioid cells, macrophages, and CD4 + T lymphocytes." (PMID 39904950, 2025). "In the absence of CD4+ T cells, TB granulomas were again dominated by pro-inflammatory neutrophil-derived and type 1 IFN signaling." (PMID 39214090, 2024). "A great deal of CD3+ and CD4+ T cells have been found in other sites, such as closed necrotic, non-necrotic cellular granulomas, and central cavities of open granulomas." (PMID 38919629, 2024). "Previous studies indicated that IFNγ mediates expression and secretion of chemokines CXCL9, CXCL10, and CXCL11 in macrophages, resulting in the recruitment of CXCR3 bearing CD4+ Th cells and CD8+ Tc cells into the lung and granuloma formation in humans and mice." (PMID 39464896, 2024). "In addition, Tp potently reduced CD4+ T-cell, and to a lesser extent CD8+ T-cell and macrophage, staining in infected lungs but only reduced neutrophil numbers in the lung or in granulomas when combined with RIF." (PMID 38071218, 2023). "Like in humans, BCG supports the induction of an IFN-y and CD4+ T-cell response, however it does not seem to prevent granuloma formation and disease progression in cows compared to calves, bearing similarities to age-imprinted protection in humans." (PMID 37638020, 2023).